PLG (plasminogen)
Diseases named in the same sentence as PLG in open-access papers (continued):
Sharing a sentence is not in itself a finding about the gene and the disease.
Sepsis (24 papers, 2011 to 2025). Sepsis is defined as life-threatening organ dysfunction caused by a dysregulated host response to infection. "Plasmin formation has also been reported to have both beneficial and detrimental effects during infection and sepsis, respectively, in infection models using plasminogen deficient mice." (PMID 37700271, 2023). "PLG deficiency may lead to reduced survival rates during infection but may confer protective effects during sepsis by modulating inflammatory cytokine production." (PMID 40377310, 2025). "Lower plasminogen levels are associated with the severity of sepsis." (PMID 37569751, 2023). "Both excessive consumption of plasminogen and decreased synthesis due to sepsis-associated liver failure could be triggers of fibrinolysis impairment and the hypercoagulable state, but other mechanisms are coming to light." (PMID 37569751, 2023). "In later stages of sepsis, plasminogen consumption and decreased synthesis will lead to lower levels of circulating plasminogen." (PMID 37762481, 2023). "Thrombin generation and several other situations as hypoxia, trauma, or sepsis trigger the release of the tissue plasminogen activator (t-PA), which activates plasminogen and plasmin, leading to fibrin degradation." (PMID 38066736, 2023). "The purpose of this review is to summarize all relevant publications regarding the role of the main components of the plasminogen activation system (PAS) in the pathophysiology of sepsis." (PMID 37569751, 2023). "Low plasminogen concentrations preceded development of thrombocytopenia in a case series of humans with sepsis, and have been described in dogs with DIC due to cancer, pancreatitis and sepsis." (PMID 36876005, 2023). "In severe sepsis, fibrinolysis and coagulation inhibitors are depleted, supported by a decrease in major coagulation inhibitors (e.g., PC and anti-thrombin) and plasminogen, along with an increase in PAI-1, our marker of interest, as shown in previous studies." (PMID 29967603, 2018). "Median plasminogen activity levels were reduced in sepsis (81 %) and especially in CTS (54 %) and cirrhosis (68 %), while being elevated in a pregnant state (178 %) when compared to healthy volunteers (119 %)." (PMID 26770073, 2016). "To study how plasminogen affects the cytokine production, we studied the profiles of inflammatory cytokines in the sera of WT and plg-/- mice during infection and sepsis." (PMID 21931850, 2011). "Herein, we investigated the role of the plasminogen/plasmin (Plg/Pla) system during sepsis." (PMID 36917195, 2023). "Moreover, the IL-6 levels in plg+/- mice were approximately half of those in WT mice at 24 h after induction of sepsis, indicating that the relative levels of plasminogen also affect cytokine production." (PMID 21931850, 2011). "The authors concluded that the consumption of plasminogen and coagulation inhibitors was the principal mechanism leading to fibrinolysis resistance in the more severely ill patients and they demonstrated that the same mechanisms occurred in sepsis due to several different pathogens." (PMID 36765421, 2023). "The reduction in plasminogen levels observed in sepsis may be due to several mechanisms." (PMID 37569751, 2023). "The presence of a higher level of uPA in plasma samples from patients with sepsis could be considered a protective factor against sepsis, as uPA is reported to be capable of regulating inflammation and immune responses and inducing plasminogen activation." (PMID 37569751, 2023). "Through the conversion of plasminogen to plasmin, uPA may play an antithrombotic role in sepsis." (PMID 21219633, 2011). "In addition, during sepsis, since the IL-6 levels are highest in WT mice, intermediate in plg+/- mice, and lowest in both tPA-/-/uPA-/- and plg-/- mice, the increase in cytokine levels appears to be related not only to levels of plasminogen but also to levels of active plasmin." (PMID 21931850, 2011).
Sepsis (continued). "In the current study, we have used single gene-deficient mice lacking plasminogen (plg-/-), uPA (uPA-/-), tPA (tPA-/-), and doubly deficient mice lacking both tPA and uPA (tPA-/-/uPA-/-), to study the functional roles of plasmin during S. aureus-induced infection and sepsis." (PMID 21931850, 2011). "In our study, patients had very different levels of fibrinogen and possibly also of plasminogen, which unfortunately was not measured but is known to be reduced in severe sepsis/septic shock." (PMID 26308340, 2015). "In this study, by using mice lacking genes for plasminogen, tissue-type plasminogen activator (tPA), and urokinase-type PA (uPA), we have investigated the functional roles of active plasmin in infection and sepsis." (PMID 21931850, 2011). "Moreover, sepsis induced, and compstatin counteracted, the expression of the tissue plasminogen activator (PLAT) and six acute-phase reactant serpins, including SERPINE1 (PAI-1, the main plasma inhibitor of plasminogen activation), which confirmed our previous protein quantification." (PMID 26337158, 2015). "Fibrinolytic pathway proteins including AP, plasminogen and TAFI have been studied in dogs with babesiosis, cancer and endocrinopathies, but similar studies of fibrinolysis in dogs with sepsis have not been performed." (PMID 36876005, 2023).
thrombosis (21 papers, 2006 to 2025). "While thrombosis has been observed in PLG-deficient individuals, it has mostly been reported in isolated cases within families." (PMID 38984351, 2024). "Plasminogen was negatively associated with thrombosis (OR = 0.96, 95% CI = 0.94–0.99, p = 0.011), indicating that higher levels of plasminogen were associated with a lower risk of dying." (PMID 37629265, 2023). "Plasmin plays a role in fibrin clot degradation, and mutations in PLG were associated with severe thrombosis." (PMID 36777185, 2023). "As the levels of coagulation factors and plasminogen in neonates are low, they are at risk for both hemorrhage and thrombosis." (PMID 32358367, 2020). "Similar findings were noted in a series of 277 Dutch patients with deep vein thrombosis: 8.3 percent had an isolated deficiency of antithrombin, protein C, protein S, or plasminogen compared to 2.2 percent of controls." (PMID 16968541, 2006). "Plasminogen (PLG) deficiency is associated with susceptibility to thrombosis." (PMID 38350915, 2024). "Apolipoprotein(a) promotes arterial and venous thrombosis through mechanisms such as increased oxidized phospholipid levels, accumulation in vascular walls, and impaired plasminogen activation." (PMID 41211516, 2025). "The thrombogenic properties of Lp(a) result from the homology between apolipoprotein(a) and plasminogen, which compete for the same binding sites on endothelial cells to inhibit fibrinolysis and promote intravascular thrombosis." (PMID 35053174, 2021). "A case study of a patient with leukemia who received L-asparaginase therapy described the development of vein thrombosis due to therapy-induced reductions of plasma plasminogen and antithrombin III levels in the patient." (PMID 33632136, 2021). "Thrombolytic therapies with plasminogen activators (t-PA, SK and UK) have high potential in treating thrombosis, facilitating the use of plasminogen activators in medicine today, but their high prices and side effects limit their wide application." (PMID 31239529, 2019). "For example, Plasminogen (PLG) is a target indicated for multiple diseases: Conjunctivitis Allergic, Myocardial Infarction, Pulmonary Embolism and Venous Thrombosis." (PMID 27824084, 2016). "Thrombolytic agents, by acting as plasminogen activators, break down the fibrin polymers of an acute thrombosis by converting plasminogen to plasmin, which in turn breaks down fibrin, releasing fibrin degradation products." (PMID 18559104, 2008). "Thrombosis has been reported in young patients when the plasminogen concentration is less than 40 percent of control values." (PMID 16968541, 2006). "Therefore, any mutation in PLG that directly or indirectly affects the balance between closed and open forms may change the plasminogen interactome and its functions, potentially increasing the risk of thrombosis, including microvascular thrombosis as seen in TMA." (PMID 41169534, 2025). "In a study of 23 subjects with homozygous mutations in the PLG gene and little or no detectable plasmin, 96% had clinical inflammation of the conjunctivae (ligneous conjunctivitis) but 0% had experienced venous thrombosis." (PMID 32545518, 2020). "It converts plasminogen into plasmin and is used clinically to treat thrombosis." (PMID 25886739, 2015). "Importantly, long retracted clots which are found in peripheral arterial occlusion (PAO) and deep-vein thrombosis (DVT), often lack plasminogen." (PMID 29206190, 2017).
diabetes (20 papers, 2007 to 2025). "We identified glutamate‐associated genes using GWAS analysis, and PLG was identified as a regulator of glutamate‐related diabetes onset." (PMID 37314019, 2023). "Increased SARS-CoV-2 pathogenicity, which has been connected to diabetes, has been linked to higher plasminogen levels." (PMID 36984473, 2023). "F2 and F9 were associated with cardiovascular disease (CVD) and diabetes, whereas PLG was only related to apoptosis, which is involved in ischemic stroke pathogenesis." (PMID 32466277, 2020). "Plasminogen is thought to be increased in the urine as an early sign of renal damage before microalbuminuria occurs in patients diagnosed with pediatric diabetes mellitus, and this can also be a therapeutic target to slow disease progression." (PMID 40576805, 2025). "Through GWAS analysis, PLG genes that were significantly associated with glutamate were identified, and the effects of glutamate and PLG on diabetes were investigated via functional studies using cell and mouse models." (PMID 37314019, 2023). "Fibrin formed in patients with diabetes binds tissue plasmin activator and plasminogen to a lesser extent than in healthy person, which is yet more aggravated by an increased plasmin inhibitor." (PMID 34064568, 2021). "tPAI-1 is an inhibitor of plasminogen, which regulates the systemic fibrinolytic system, and the levels indicate microvascular injury due to various conditions, including diabetes mellitus." (PMID 34736457, 2021). "Higher plasminogen levels have been associated with an increase in SARS-CoV-2 pathogenicity, which has been linked to diabetes." (PMID 35004020, 2021). "The hyperglycaemic environment in diabetes is responsible for glycation of plasminogen, which compromises protein function." (PMID 28279217, 2017). "Known factors contributing to the prothrombotic fibrin clot phenotype observed in patients with diabetes represent increased plasma fibrinogen concentrations and enhanced glycation of the fibrinogen or plasminogen molecules." (PMID 26357663, 2015). "Therefore, our results indicate that insulin resistance induced by excessive glutamate can contribute to PLG activation, a major factor in fibrinolysis, and PLG is involved in the onset of glutamate‐related diabetes." (PMID 37314019, 2023). "Moreover, glycosylated plasminogen in diabetes directly affects fibrinolysis by reducing plasmin generation and impairing functional protein activity, resulting in impaired fibrinolysis." (PMID 35382802, 2022). "Hence, over the past few decades significant interest has been generated on the effects of diabetes on fibrinolytic system in blood which involves plasminogen activators, particularly t-PA and its inhibitor PAI-1." (PMID 36057550, 2022). "A number of abnormalities in the fibrinolytic system have been reported in diabetes including elevated PAI-1 and TAFI levels, and deranged plasminogen function." (PMID 28279217, 2017). "We also noted that some proteolytic fragments of plasminogen can induce upregulation of pigment epithelium-derived factor (PEDF) expression, a potent angiogenic inhibitor in experimental diabetes." (PMID 17293777, 2007). "Regarding differences among the non-diabetic, diabetes remission, and persistent diabetes groups, considering the samples obtained before and after surgery as a whole, we found different abundances in nine spots from five proteins: CP, SERPINA1, ITIH4, plasminogen (PLG), and FGG." (PMID 34501327, 2021).
atherosclerosis (19 papers, 2004 to 2025). A disease characterized by the build-up of fatty material and calcium deposition in the arterial wall resulting in partial or complete occlusion of the arterial lumen. "PLG encodes plasminogen which can contribute to atherosclerosis by modulating, cell migration, extracellular matrix structure, vascular smooth muscle cell (VSMC) function, and inflammation." (PMID 40175777, 2025). "It has been reported that a plasminogen (Pg) deficiency (Plg−/−) exacerbates the progression of atherosclerosis in Apoe−/− mice." (PMID 34944648, 2021). "The duality and uniqueness of Lp(a), which make Lp(a) homologous to both LDL-C and PLG, most likely underlie the different but related atherosclerosis mechanism theories." (PMID 32099678, 2020). "Deficiency of plasminogen in mice (Plg-/-) results in markedly discrepant effects on atherosclerosis." (PMID 15574198, 2004). "Lp(a) includes apo B-100, a low-density lipoprotein-like fraction believed to promote atherosclerosis, and apolipoprotein A fraction, which is similar to plasminogen and may mediate an increased risk of thrombosis." (PMID 38066475, 2023). "Although the precise mechanism by which PLG variants may affect atherosclerosis needs to be elucidated, genetic variation in this gene may delay and disrupt the process of fibrin resolution leading to clot buildup." (PMID 32685059, 2020). "Due to similarities with plasminogen structure, Lp (a) inhibits the binding of plasminogen to fibrin and endothelial cells, promoting thrombosis and atherosclerosis." (PMID 35783660, 2022). "Some of the RORα-modulated genes are involved in physiological functions such as lipid metabolism (LPA, NR1D2, ADIPOQ also known as adiponectin) and inflammation (ADIPOQ, PLG), but also in related cardiovascular diseases such as atherosclerosis." (PMID 21818335, 2011). "Oxidized phospholipids (OxPLs) contribute to atherosclerosis by promoting inflammation and oxidative modification of lipoproteins, while plasminogen (PLG) plays a central role in fibrinolysis that can be modified by OxPLs, potentially affecting thrombotic risk." (PMID 40994740, 2025). "About 80% of the amino acids in apo(a) are homologous with those of plasminogen, suggesting a possibly thrombolytic effect which might both promote atherosclerosis and trigger acute thrombotic occlusions." (PMID 15601478, 2004). "It plays important roles in the development of atherosclerosis and thrombosis as it is similar to low-density lipoprotein cholesterol (LDL-C) and plasminogen." (PMID 36465632, 2022). "We have recently shown that PLG is an effective sterol acceptor through ABCA1, and this could be the mechanism by which PLG contributes to atherosclerosis." (PMID 30622162, 2019).
hypercoagulability (19 papers, 2006 to 2025). "Production of anti-plasminogen and plasminogen activator autoantibodies can inhibit fibrinolysis and predispose to fibrinoid necrosis and thrombophilia." (PMID 38500101, 2024). "Background and aims: Dysplasminogenemia is a rare heritable disease caused by plasminogen (PLG) gene defects resulting in hypercoagulability." (PMID 37065478, 2023). "The PLG gene encodes a secreted blood zymogen that is primarily expressed in liver tissue, and abnormality of this gene contributes susceptibility to thrombophilia." (PMID 31870308, 2019). "They suggested that this impaired fibrin-mediated plasminogen activation is most likely the cause of thrombophilia among affected patients." (PMID 16968541, 2006). "Plasminogen deficiencies can also lead to thrombophilia in patients." (PMID 16968541, 2006). "One study described a trend of decreased plasminogen activity in cats with acquired heart disease, while others have found evidence of hypercoagulability, hyperfibrinogenemia, and increased blood viscosity in cats with HCM hypertrophic cardiomyopathy." (PMID 40509097, 2025). "Nephrotic syndrome is associated with hypercoagulability due to increased clotting factors V, VII, and VIII, fibrinogen, and 2-antiplasmin and depletion of factors IX and XII, antithrombin III, and plasminogen." (PMID 26793398, 2015). "Patients with nephrotic syndrome are always in a state of hypercoagulability and hyperfibrinolysis, which could be caused by the increased synthesis of blood coagulation factors in liver, the increased consumption of antithrombin, and the decreased levels of protein S, protein C and plasminogen." (PMID 22738421, 2012). "Blood hypercoagulability can be an outcome of inhibition of the plasminogen system." (PMID 36295093, 2022). "Decreased plasminogen might therefore be the result of its increased use by the parasite and/or consumption due to the hypercoagulability reported in babesiosis." (PMID 28363279, 2017). "Downregulation of plasminogen, which might explain the lower levels observed in LVA patients, could therefore attribute to the hypercoagulation state often observed in AF." (PMID 30496173, 2018). "Patients in group SOFA > 10 had lower plasminogen levels than patients with SOFA <10, which may represent less fibrinolysis activity during a state of hypercoagulability and, consequently, a greater probability of microthrombi formation in the microcirculation of different organs." (PMID 33320874, 2020).